SLC25A41 (solute carrier family 25 member 41)
Description:
Calcium-independent ATP-Mg/Pi exchanger that catalyzes the electroneutral exchange of Mg-ATP or free ADP against an hydrogenphosphate and participates in the net transport of adenine nucleotides across the mitochondria inner membrane.
Synonyms: SCaMC-3L; FLJ40442; MGC34725; APC4
Tractability: Antibody: UniProt predicts a signal peptide or a membrane-spanning region.
Gene: Protein-coding gene on chromosome 19 (6,426,037 to 6,433,779, reverse strand). Ensembl gene ENSG00000181240.
Subcellular location: Mitochondrion inner membrane
Gene Ontology:
Molecular function: ADP transmembrane transporter activity; ADP:phosphate antiporter activity; ATP transmembrane transporter activity; ATP:phosphate antiporter activity; nucleobase-containing compound transmembrane transporter activity; organophosphate ester transmembrane transporter activity
Biological process: ADP transport; ATP transport; mitochondrial ADP transmembrane transport; mitochondrial ATP transmembrane transport; transmembrane transport
Cellular component: mitochondrial inner membrane; mitochondrion
Genetic constraint (gnomAD): Loss-of-function variants: 39 observed, 38.73 expected, observed/expected ratio (o/e) 1.01, 90% interval 0.78 to 1.32. The upper end of that interval is the gene's LOEUF score, 1.32, which puts it in group 5 of 6, group 1 being the genes least tolerant of losing a copy. Missense variants: 492 observed, 496.5 expected, observed/expected ratio (o/e) 0.99, 90% interval 0.92 to 1.07. Synonymous variants: 190 observed, 211.06 expected, observed/expected ratio (o/e) 0.9, 90% interval 0.8 to 1.01.
Homologues: Orthologues: chimpanzee SLC25A41 (98% identical), dog SLC25A41 (78% identical), pig SLC25A41 (76% identical), rat Slc25a41 (72% identical), mouse Slc25a41 (71% identical), guinea pig SLC25A41 (69% identical), macaque SLC25A41 (69% identical). Paralogues in human: SLC25A23 (55% identical), SLC25A25 (49% identical), SLC25A24 (48% identical), SLC25A12 (21% identical), SLC25A13 (21% identical), SLC25A6 (17% identical), SLC25A29 (17% identical), SLC25A31 (17% identical), SLC25A39 (17% identical), SLC25A4 (17% identical), SLC25A28 (17% identical), SLC25A33 (16% identical), and 37 more.
Diseases named in the same sentence as SLC25A41 in open-access papers:
SLC25A41 is named in the same sentence as 8 diseases in open-access papers, as found by Europe PMC text mining. Sharing a sentence is not in itself a finding about the gene and the disease. The quoted sentences say what the papers report.
breast invasive cancer (1 paper, 2022). "Moreover, SLC25A7 and SLC25A27 had decreased expression in breast invasive cancer while SLC25A41 was increased." (PMID 36254139, 2022).
cervical squamous cell carcinoma (1 paper, 2022). A squamous cell carcinoma arising from the cervical epithelium. "Some genes of SLC25 were associated with poor prognosis of patients in cervical squamous cell carcinoma and endocervical adenocarcinoma, including SLC25A4, SLC25A5, SLC25A8, SLC25A14, SLC25A12, SLC25A23, and SLC25A41." (PMID 36254139, 2022).
lung adenocarcinoma (1 paper, 2022). A carcinoma that arises from the lung and is characterized by the presence of malignant glandular epithelial cells. "In lung adenocarcinoma, SLC25A7 and SLC25A25 had decreased expression while SLC25A41 was elevated." (PMID 36254139, 2022).
ovarian carcinoma (1 paper, 2022). A malignant neoplasm originating from the surface ovarian epithelium. "Relatively high mutation rates were also observed in ovarian cancer cell lines for SLC25A13, SLC25A24, SLC25A41, and SLC25A23 and in skin cancer cell lines for SLC25A13, SLC25A8, and SLC25A12." (PMID 36254139, 2022).
SLC25A41 also shares sentences with these, for which no sentence is quoted: endocervical adenocarcinoma (1 paper); melanoma (1); skin cancer (1); tumor (1).